IL10 (interleukin 10)
Diseases named in the same sentence as IL10 in open-access papers (continued):
Sharing a sentence is not in itself a finding about the gene and the disease.
Sepsis (continued). "We observed that outcomes of sepsis progression could be improved with IL-10 at a medium level in an early stage of infection (between the first 3 hrs and the first 6 hrs after infection)." (PMID 26446682, 2015). "Interestingly, GG genotype of IL-10 (−1082) was predominant in sepsis patients and higher producer (11.6 ± 4.7 vs. 84.5 ± 37.5 pg/ml, HC vs. sepsis, p < 0.001)." (PMID 26561011, 2015). "Interestingly, the varied amount of TNF-α in all three groups: healthy controls, non-sepsis and sepsis patients showed an example of expression masking of the genotype with a high producer genotype of IL-10 in these patients." (PMID 26561011, 2015). "Interestingly, we noticed trauma patients who had (G to A) substitution at IL-10(−1082) positions were protective for the sepsis and produced significantly lower level of IL-10 in comparison to GG genotype patients." (PMID 26561011, 2015). "These associations support the hypothesis that an increase in levels of IL-β, TNF-α and IL-10 secretion due to genetic variation in their genes may contribute to the development of sepsis after severe trauma by affecting the induced immune response." (PMID 26561011, 2015). "During sepsis, Wnt 5a concentration in sera of patients was elevated and Wnt 5a was also found to induce macrophage differentiation to a tolerogenic phenotype, which was related to induction of IL-10 and suppression of NF-κB signaling." (PMID 25821827, 2015). "For example, IL-10 suppresses I-κB kinase activity, blocks NF-κB activation, reduces pro-inflammatory mediator production, improves bacteria-induced lung inflammation, and protects animals against lethal endotoxemia and sepsis." (PMID 26103469, 2015). "Moreover, cytokine IL-8 enabled a significant differentiation between sepsis and viremia, sepsis and bacteremia, and bacteremia and viremia whereas IL-10 made a distinction between sepsis and viremia possible." (PMID 26315105, 2015). "In addition, IL-8 facilitates a significant distinction between bacteremia and viremia (P = 0.0064), and IL-10 can differentiate between sepsis and viremia (P = 0.005)." (PMID 26315105, 2015). "Despite a ghrelin-induced leptin elevation and the ability of leptin to generally improve cytokine response in sepsis the increase in TNFα with simultaneous IL-10 and IL-1ß decline may be a sign of suppression of an early and effective immune response." (PMID 25844479, 2015). "In bacterial infections, IL-10 is also produced during sepsis." (PMID 24839609, 2014). "Early T-cell cytokine-production capacities of the antiinflammatory cytokines, IL-4 and IL-10, were also lower in sepsis patients as a whole compared with healthy controls (2.9 (0.7 to 5) versus 8.2 (3 to 10) pg/ml; P = 0.03; and 23 (6 to 41) versus 68 (26 to 126) pg/ml, P = 0.02), respectively." (PMID 25005517, 2014). "TsES also have a regulatory function and increase IL-10 and TGFβ1, which could regulate the inflammatory response during sepsis." (PMID 25054155, 2014). "Moreover, IL-10 predominance over proinflammatory mediators is correlated with poor patient survival after sepsis." (PMID 24804272, 2014). "Factors other than IL-10 may be more effective in inhibiting inflammation in the early phase of sepsis." (PMID 24886652, 2014). "At T0, serum concentrations of Resistin, NGAL, IL-6, IL-10 and IL-8 were significantly higher in patients with severe sepsis/septic shock compared to patients with uncomplicated sepsis (p = 4.5×10−5, p = 2.5×10−4, p = 0.002, p = 0.018 and p = 9.0×10−4 respectively, Mann Whitney)." (PMID 25343379, 2014). "IL-6 and IL-10 are important proinflammatory and anti-inflammatory cytokines during sepsis course." (PMID 24672147, 2014). "Pretreatment of mice, or murine macrophages, with AM before challenge with endotoxin suppressed the production of pro-inflammatory cytokines (e.g., TNFα, IL-1β, CCL5, IL-12) while promoting IL-10 production, and reduced mortality due to cecal-ligation and puncture-induced sepsis." (PMID 25309541, 2014).
Sepsis (continued). "The IL-10 increase could be a biological presentation similar to that of the compensatory anti-inflammatory response syndrome (CARS) in sepsis, in which the peripheral blood inflammatory milieu could be accompanied by anti-inflammatory molecules." (PMID 25254368, 2014). "However, in patients with severe sepsis/septic shock, there were statistically significant changes over time in serum concentrations of Resistin, IL-6, IL-10, IL-8 and MCP-1 (p = 0.024, p = 3.5×10−6, p = 5.0×10−4, p = 0.002, p = 0.049, Skillings-Mack)." (PMID 25343379, 2014). "Bone marrow-derived mesenchymal stem cells could attenuate sepsis by releasing prostaglandin E2, which reprogrammed macrophages to increase interleukin (IL)-10 production." (PMID 24684532, 2014). "IL-10 and Resistin mRNA levels were also elevated at T0 in severe sepsis/septic shock patients compared to those with uncomplicated sepsis but these differences were not statistically significant after Bonferroni correction (p = 0.035 and p = 0.056, respectively, Mann Whitney)." (PMID 25343379, 2014). "IL-6 and IL-10 are important proinflammatory and anti-inflammatory cytokines in sepsis." (PMID 24672147, 2014). "Furthermore, the later stages of sepsis are characterized by immunosuppressant interleukins such as IL-10 and IL-4." (PMID 25399401, 2014). "Many of the canonical pro-inflammatory pathways were activated in response to CLP-induced sepsis, including cytokine signaling (IL-10, IL-8 and IL-6), the NF-κB pathway, the pattern recognition pathway (Toll-like receptors), and the acute phase response pathway." (PMID 24732911, 2014). "Finally, even if some cytokines, such as TNF and IL-10, are produced rapidly after the onset of sepsis, most of these proteic biomarkers need few hours to be generated, secreted and then, detected." (PMID 24658436, 2014). "The anti-inflammatory effects of IL-10 may be related to the decreased hepatic microvascular disturbances following sepsis in iNOS knockout mice." (PMID 23076073, 2013). "Next, to determine whether NOD2-mediated IL-1β and IL-10 production plays a critical role in C5a generation during sepsis, we administered rIL-1β or rIL-10 to WT or Nod2−/− mice 4 h or 12 h after CLP, respectively." (PMID 23675299, 2013). "Administration of rIL-1β to Nod2−/− mice enhanced serum and peritoneal IL-10 levels during sepsis." (PMID 23675299, 2013). "Furthermore, NOD2-mediated IL-1β and IL-10 production also suppressed LPS-mediated cytokine production by peritoneal immune cells during CLP-induced sepsis." (PMID 23675299, 2013). "The protective role of IL-10 in animal sepsis may be due to its antagonistic effect on the production and overall functioning of TNF." (PMID 23548047, 2013). "In accordance with these reports our study has highlighted the prognostic and early diagnostic value of IL-10 and sCD25: we believe that in the near future these markers could become valid tools for the management of patients with bacteremic SIRS and sepsis." (PMID 23561467, 2013). "Treg, IL-6, and IL-10 were higher in patients with septic shock than in patients with sepsis." (PMID 24249974, 2013). "Next, to explore whether IL-10 production regulates C3a and C5a levels during sepsis, we measured those levels and survival rates in Il-10−/− and Il-1r−/− mice with CLP." (PMID 23675299, 2013). "Furthermore, the IL-10/TNF-alpha ratio has been proposed as a prognosis indicator in sepsis during leptospirosis." (PMID 24130911, 2013). "IL-10 was significantly decreased in the Pep 2.5 group (P = 0.002) but not in the Pep 4 (P = 0.111), polyB (P = 0.11) or Pep 8 (P = 0.073) groups compared to the sepsis-control group." (PMID 23302299, 2013). "However, our experiments demonstrated that the levels of IL-6 and TNF-α in serum and peritoneum, and cytosolic IL-1β and IL-10 expression in macrophages were similar between WT and Nod2−/− mice during sepsis." (PMID 23675299, 2013).
Sepsis (continued). "High IL-10 levels have been associated with a worse outcome after severe sepsis, whereas TNF-α and IL-6 have not." (PMID 23561467, 2013). "Fourth, rIL-1β administration to Nod2−/− mice increased IL-10 and C5a levels during sepsis." (PMID 23675299, 2013). "In addition, levels of several inflammatory cytokines (TNF-α, IL-10, IL-1β), described as markers of sepsis, were reduced in galectin-3−/− mice." (PMID 23527230, 2013). "Therefore, it is feasible that NOD2-mediated signals induce IL-1β and IL-10 production by immune cells during sepsis." (PMID 23675299, 2013). "However, high level of IL-10 can also have an adverse effect by increasing the likelihood of sepsis." (PMID 22529517, 2012). "Although IL-10 level may have statistical relation to sepsis or renal dysfunction, the generally accepted critical level that would enable to unambiguously distinguish between patients with worse or good prognosis does not exist." (PMID 22529517, 2012). "Increased level of IL-10 along with the medical treatment (Ampicillin-sulbactam) of our patients might have prevented the onset of sepsis." (PMID 22529517, 2012). "In addition to the apparent but not significant decreased induction of anti-inflammatory cytokines, CD1a−negative DC from septic patients tended to induce IFN-γ production in the context of sepsis where anti-inflammation predominates with high serum IL-10." (PMID 23071758, 2012). "Plasminogen activator inhibitor-1, interleukin (IL)-1, IL-6, IL-8, and IL-10, and tumor-necrosis-factor-alpha mediate insulin resistance and are elevated in sepsis, while retinol-binding protein-4 concentrations are significantly reduced in sepsis." (PMID 22272381, 2012). "In addition to actions on regulatory T-cells, in an experimental model of sepsis MSCs were shown to induce macrophage reprogramming into a regulatory profile, with the ability to produce IL-10." (PMID 22432015, 2012). "Nonetheless, IL-10 production from peripheral blood mononuclear cells (PBMCs) in patients with severe sepsis remains unclear." (PMID 21939530, 2011). "Furthermore, in both genotypes of mice, IL-10 levels were significantly higher in sepsis than in infection." (PMID 21931850, 2011). "In addition, we also found that TNF-α, IL-6, and IL-10 levels were significantly lower in plg-/- mice than in WT mice during sepsis." (PMID 21931850, 2011). "Moreover, PD-L1 blockade significantly improved survival, prevented sepsis-induced depletion of lymphocytes, increased tumor necrosis factor-alpha and IL-6 productions, decreased IL-10 production, and enhanced bacterial clearance in mice after CLP." (PMID 21418617, 2011). "We hypothesized that IDO activity in sepsis would be related to plasma interferon-γ, interleukin-10, T cell lymphopenia and impairment of microvascular reactivity, a measure of endothelial nitric oxide bioavailability." (PMID 21731667, 2011). "Plasma IFN-γ, IL6 and IL10 were all significantly increased in patients with sepsis." (PMID 21731667, 2011). "IL-10 level is increased in patients with sepsis and can predict mortality." (PMID 21939530, 2011). "It is therefore important to investigate the effect of exercise on IL-10 in sepsis." (PMID 22035174, 2011). "In a less severe sepsis model, Trif-deficient mice have reduced cytokine production including TNFα, IL-6, and IL-10 suggesting Trif signaling may contribute to systemic inflammation in a mild form of animal sepsis." (PMID 21977329, 2011). "Sepsis (odd ratio 5.24), among the clinical variables and IL-10 (odd ratio 1.24, 95% confidence interval (CI): 0.00–2.19) and transferrin (odd ratio 0.45, CI: 0.00–6.43) among the stress and nutritional mediators were independently associated with the development of MOSF (P < .0001)." (PMID 20490277, 2010). "These might be the reason why the survival rate could be elevated when inflammation was inhibited by IL-10, and why the level of cytokine was correlated inversely with survival time in patients with sepsis." (PMID 20937098, 2010).
Sepsis (continued). "The IL-10/TNFα ratio has been proposed as a prognosis indicator in sepsis and in leptospirosis." (PMID 20076757, 2010). "Congruently, risk alleles associated with increased nuclear factor κB (NF-κB) activation upon TLR1 stimulation in previous studies, were related with reduced interleukin-10 and elevated C-reactive protein serum levels during the first week of sepsis development." (PMID 21048935, 2010). "Levels were higher in sepsis than in non-sepsis patients with a clear association to markers of the inflammatory response including white blood cell count, CRP, procalcitonin, and with the proinflammatory cytokines IL-6, IL-10, and TNF-α." (PMID 19545363, 2009). "It suggests that lower producers of IL-10 might be sensitive to the development of sepsis and MODS due to its ability to suppress inflammation." (PMID 19939284, 2009). "IL-10 is an important contributor to the dysregulated immune system that is observed in sepsis." (PMID 19641602, 2009). "IL-10 is an immunoregulatory cytokine that is released primarily by macrophages during sepsis." (PMID 19641602, 2009). "Thus, IL-10 can potentially counterbalance the detrimental effects of excessive cytokine production in sepsis." (PMID 16611358, 2006). "Genetic variations within the TNF and IL-10 genes may influence mortality rates in patients with sepsis." (PMID 16859504, 2006). "Paradoxically, while IL-10 plays a protective role by limiting tissue damage, elevated levels can reflect a compensatory anti-inflammatory response that impairs host defense, as commonly observed in early sepsis as a marker of severity and impending immunosuppression." (PMID 40869413, 2025). "Moreover, sepsis-related anti-inflammatory cytokines primarily include IL-4, IL-10, and IL-37." (PMID 40718494, 2025). "Besides IL-10, we demonstrated that the PD-1/PD-L1 axis is part of the PC regulatory armamentarium in sepsis inasmuch as PD-L1 expression is upregulated on sepsis-induced PCs and anti-PD-L1 blocking antibodies partially alleviated PC inhibitory function ex vivo." (PMID 40155394, 2025). "Since IL-10 and TGF-β enhance sepsisimmunosuppression and are associated with worse outcomes, our findings suggestthat targeting S100A9 may mitigate the immunosuppressiveeffects of MDSCs in late sepsis." (PMID 40458301, 2025). "Thus, in the previously published study we surmised that CD4+ Foxp3+ IL-10-producing cells could be mechanistically responsible for the observed increase in sepsis survival in CD28 agonist-treated animals." (PMID 38633258, 2024). "Hence, IL-10 has an important role in sustaining DEL-1 production under sepsis." (PMID 38263289, 2024). "To determine whether differences in DEL-1 expression observed in different tissues during neonatal sepsis reflected respective changes in IL-17A and IL-10, we measured IL-17A and IL-10 mRNA expression in tissue extracts from neonates 6 hours following exposure to CS-induced sepsis." (PMID 38263289, 2024). "The latest predictive model suggests that age, neutrophils, lymphocytes, IL-2, IL-10, and procalcitonin are the major variables in predicting progression to severe illness, particularly white blood cell count and procalcitonin inflammatory index, which are commonly used in clinics to judge sepsis." (PMID 38127118, 2024). "In another study using the CLP model, mice with CB2R knocked out in CD4+ T cells showed improved survival and increased IL-10 production upon CB2R activation, indicating that CB2R activation in CD4+ T cells may enhance sepsis susceptibility by inhibiting IL-10 production." (PMID 38775488, 2024). "This sepsis-induced immunosuppression is typically characterized by dysfunctional monocytes, which show a decreased release of pro-inflammatory cytokines such as tumor necrosis factor α (TNFα), IL-1β and IL-6 upon stimulation with LPS and an enhanced secretion of anti-inflammatory IL-10." (PMID 37759239, 2023).
Sepsis (continued). "Based on our results, IL10 gene hypomethylation also correlated with elevated IL-10 levels in plasma of septic patients, as we recently demonstrated, supporting the idea that alterations in methylation levels induce changes in the immune system response during sepsis progression." (PMID 38235139, 2023). "Therefore, it is speculated that matrine may also exert anti-inflammatory effects by targeting IL-10 in IE and sepsis." (PMID 38332910, 2023). "However, a massive spill of these pro-inflammatory cytokines, and/or overproduction of some anti-inflammatory cytokines (e.g., IL-10), during sepsis could be detrimental." (PMID 37107001, 2023). "In addition, anti‐inflammatory mediators, such as IL4 and IL10, are also released during sepsis, a process that not only suppresses the proinflammatory cascade but also leads to a state of relative immunosuppression in patients with sepsis." (PMID 37060578, 2023). "Bacteremia coinfections with malaria could enhance the clinical severity of anemia and sepsis by decreasing cyclooxygenase (COX)-2 and prostaglandin E2 (PGE2) expression, and these mediators were associated with TNF-α, IFN-γ, and IL-10 production in coinfected individuals." (PMID 36716305, 2023). "Here, after the induction of sepsis, IL-10 levels were attenuated in OSMR KO mice following the induction of FIP, as were the levels of the pro-inflammatory cytokines IL1β, IL-6, TNF, and KC, which may reflect a more balanced attenuation of inflammation with improved survival." (PMID 36831019, 2023). "In addition, IL-10 levels are important because of the role of the anti-inflammatory IL-10 by inhibiting the expression of pro-inflammatory mediators such as TNF-α and IL-1β, and by conferring diminished resistance to pathogenic organisms during sepsis." (PMID 38235139, 2023). "In murine models of LPS-induced sepsis and bacterial sepsis, B-1 cell-deficient mice showed exacerbated sepsis severity and increased mortality, accompanied by increased levels of proinflammatory cytokines TNF-α and IL-6 and decreased levels of IL-10 in the plasma, lung, and gut." (PMID 36425582, 2022). "Additionally, IL-10 and interferon gamma-induced protein (IP-10) on day four could only minimally enhance PerCI prediction in patients with postoperative sepsis." (PMID 36325351, 2022). "On the other hand, inhibition of IL-10 during course of sepsis may also be beneficial." (PMID 35563475, 2022). "Adoptive transfer of B1a cells into septic mice markedly attenuated systemic inflammation and organ damage, and ultimately improved survival, in which IL-10 produced from B1a cells plays a key protective role because the mice treated with IL-10-deficient B1a cells were not protected against sepsis." (PMID 36425582, 2022). "In this study, cytokines TNF, IL-6, IL-10, IFN-γ, IL-27, alarmins Hsp72 and Hsp90, and markers associated with inflammation (CRP, procalcitonin, lactate) and stress (glucose) exhibited early-onset induction, which was strongly correlated with an increased TOS/TAC ratio in sepsis." (PMID 35204114, 2022). "The scores corresponding to the column line plots were 48 for IL-10 ≥ 2.11, 69 for IL-17 ≥ 1.69, and 100 for IL-17 ≥ 1.51, respectively, and the total scores of 22, 44, 60, 72, 83, 95, 107, 122, and 145 corresponded to a probability of sepsis of 10–90%, respectively." (PMID 35937269, 2022). "Moreover, low IL‐10 production after ex vivo LPS stimulation of whole blood from patients with sepsis may be related to persistent organ dysfunction." (PMID 36444621, 2022). "IL-6 and IL-10 levels between Gram bacteria types in severe subgroups (bloodstream infectious patients with higher serum cytokines and sepsis patients with ARDS) might reflect the existence of other inflammatory responses that is independent of the initial bacterial infection." (PMID 36544765, 2022).